LINC00654 (long independently transcribed non-coding RNA 654)
Synonyms: LINC01729
Gene: Long non-coding RNA gene on chromosome 20 (5,481,788 to 5,526,741, reverse strand). Ensembl gene ENSG00000205181.
Diseases named in the same sentence as LINC00654 in open-access papers:
LINC00654 is named in the same sentence as 5 diseases in open-access papers, as found by Europe PMC text mining. Sharing a sentence is not in itself a finding about the gene and the disease. The quoted sentences say what the papers report.
breast carcinoma (2 papers, 2022). "For instance, SH3BP5-AS1 is a proven independent prognostic marker of head and neck squamous cell carcinoma, and upregulation of LINC00654 has been correlated with dismal OS in breast cancer." (PMID 35422758, 2022).
cancer (2 papers, 2021 to 2022). A tumor composed of atypical neoplastic, often pleomorphic cells that invade other tissues. "In this study, several ARlncRNAs included in the modeling process have been already reported in various malignant tumors, such as CARD8-AS1, AC060780.1, AC123595.1, UGDH-AS1, LINC00996, LINC00861, AL606489.1, HLA-DQB1-AS1, LINC00654, and LINC00847." (PMID 34956321, 2021).
tumor (1 paper, 2021). "In addition, the combination of several tumor markers, such as lncRNA ZFAS1, SNHG11, LINC00909, and LINC00654, can improve the accuracy of CRC diagnosis." (PMID 34778084, 2021).
LINC00654 also shares sentences with these, for which no sentence is quoted: diffuse large B-cell lymphoma (1 paper); head and neck squamous cell carcinoma (1).